SKI (SKI proto-oncogene)
Diseases named in the same sentence as SKI in open-access papers (continued):
Sharing a sentence is not in itself a finding about the gene and the disease.
Marfan syndrome (1 paper, 2021). A disorder of the connective tissue. "SKI dysfunction is causal to Shprintzen–Goldberg syndrome, a connective tissue disorder similar to Marfan syndrome, which manifests from a loss-of-function mutation in SKI’s SMAD-binding domain." (PMID 33847835, 2021).
microcephaly (1 paper, 2023). A congenital or acquired developmental disorder in which the circumference of the head is smaller than normal for the person's age and sex. "This suggests either a positional effect, indeed, deletions may be responsible for Topologically Associating Domains (TADs) disruption and chromatin disorganization leading to the deregulation of several genes or candidate genes for microcephaly as CDC42, SKI, or RERE." (PMID 36369750, 2023).
microphthalmia (1 paper, 2008). Congenital or developmental anomaly in which the eyeballs are abnormally small. "SKI is also an activator of MITF, a gene implicated in microphthalmia." (PMID 19112531, 2008).
orofacial clefting (1 paper, 2021). "Duplication of the SKI gene has not yet been linked to orofacial clefting and tooth development directly." (PMID 33732167, 2021).
prolymphocytic leukemia (1 paper, 2025). A mature B- or T- cell leukemia with progressive clinical course. "The presence of the PRDM16::SKI fusion gene was described, for the first time, in a T prolymphocytic leukemia (T-PLL) patient with a long indolent period and a late development treatment requiring disease." (PMID 40933896, 2025).
pulmonary disorder (1 paper, 2022). "Based on pathway enrichment analysis, genes altered in BPD blood cells were mainly enriched in cell cycle regulation and arrest (e.g., PPP2CA, RBL2, CENPU, CCNY, CDK6) and pulmonary disorder and developmental disorders (e.g., AGER, ITGA6, CA4, BACH2, IGFBP2, BMPR2, SKI, DAB2)." (PMID 35484630, 2022).
Tricho-hepato-enteric syndrome (1 paper, 2013). "Syndromic diarrhea/Tricho-hepato-enteric syndrome (SD/THE) is a rare and severe bowel disorder caused by mutation in SKIV2L or in TTC37, 2 genes encoding subunits of the putative human SKI complex." (PMID 23302111, 2013).
viral infection (1 paper, 2023). "Most importantly, the human orthologous (SKI) was described as a TGF-β signaling negative regulator and was found to be differentially expressed in various diseases, as well as in vitro studies, which highlighted its upregulation during viral infection." (PMID 38257883, 2023).
tumor (21 papers, 2011 to 2026). "Concerning the expression of the markers in tumor-associated microglia/macrophages and in accordance with our findings, an expression of SKI, Cables1, and DCHS1 was also described by previous studies." (PMID 37296610, 2023). "Interestingly, the SKI protein has been associated with high cellular tumours and functions to negatively regulate transforming growth factor beta (TGF-beta) by direct interaction with Smads." (PMID 31973233, 2020). "In this study, we found that increased SKI expression is associated with a better outcome, raising the possibility that it may function as a tumor suppressor gene in some cases of CLL." (PMID 22194822, 2011). "The SL of the PELO‐HBS1L and SKI complexes can thus act as a biomarker to identify tumour patients likely to be sensitive to related therapies." (PMID 41537447, 2026). "For example, the genes BCL9L or SKI—found to be up-regulated in vivo and in vitro—are potentially involved in tumor growth and initiation via modulation of the TGFβ (SKI) or WNT-β-catenin (BCL9L) pathway." (PMID 39063079, 2024). "SKI is a proto-oncogene overexpressed in tumor cells of various malignancies and hence involved in the growth, proliferation, invasion, metastasis, and tumor progression of cancer cells." (PMID 37296610, 2023). "SKI protein expression was decreased in human CC cells overexpressing miRNA‐3648, endogenous SKI protein expression was decreased in human CC tumor tissues, and endogenous SKI mRNA expression was suppressed in human CC cells characterized by rapid growth." (PMID 36114826, 2022). "Knockdown experiments suggested that SMAD4 was not necessary, but we subsequently showed that tumor cells deleted for SMAD4 or containing mutations in SMAD4 that abolish interactions with activated R-SMADs, abrogated TGF-β-induced degradation of SKI/SKIL." (PMID 33416497, 2021). "However, a large number of genes considered as oncogenes or that promote tumour growth and/or metastasis, such as SKI, EGR4, SNAI1 and CEMIP2, were also overexpressed in response to TPL." (PMID 32543350, 2020). "SKI may also localize in the cytoplasm of tumor cells, where it may interfere with TGF-β signaling by sequestering SMAD proteins and preventing their nuclear accumulation in response to TGF-β, as we demonstrated in the case of SnoN." (PMID 21211030, 2011). "This has prompted us to consider that SKI proteins may exert tumor promoter activities, by preventing the classical growth inhibitory activity exerted by TGF-β in a variety of non-malignant cell types." (PMID 21211030, 2011). "They hypothesized that the tumor suppressor activity of SKI results from its ability to mediate transcriptional repression by other known tumor suppressors, namely Mad and Rb, which interact with multiple target genes to negatively regulate cell cycle progression." (PMID 22194822, 2011). "In our study, CCRL1, SLFN13, SKI, Cables1, and DCHS1 were all shown to be regulated under TMZ-promoted dormancy and, besides tumor cells, to be expressed by endothelial cells and tumor-associated microglia/macrophages." (PMID 37296610, 2023). "We now show that SKI also functions independently of SMAD/TGF-β signaling, by activating the Hippo tumor-suppressor pathway and inhibiting the Transcriptional co-Activator with PDZ-binding motif (TAZ or WWTR1)." (PMID 33847835, 2021). "The co-repressors SKI and SKIL play important roles in a number of different cellular processes including proliferation, differentiation, transformation, and tumor progression." (PMID 33416497, 2021). "We showed that oncoprotein SKI, which is involved in CBP/p300-mediated acetylation, diminished the expression of activating ligands for the cytotoxicity receptor NKG2D on tumor cells, thereby counteracting NK cell-dependent cytotoxicity." (PMID 33023028, 2020). "The large majority of super enhancers were tumor-specific and enriched for tumor-related genes, such as PAX6, FGFRL1, FGFR1, SKI, and BOC." (PMID 30279357, 2018).
cancer (20 papers, 2009 to 2025). A tumor composed of atypical neoplastic, often pleomorphic cells that invade other tissues. "We demonstrate here that the chronic treatment (24 h) of MDA-MB-453 cells with SKi promoted the loss of SK1 (Mr∼42 kDa) expression from these cells consistent with our previous findings that SKi induces the ubiquitin-proteasomal degradation of SK1 in cancer cells." (PMID 22460268, 2012). "DPYSL2 (dihydropyrimidinase-like 2) and SKI (sphingosine kinase) were found essential in the assembly and stabilization of MT in various cell types and in cancers." (PMID 37466845, 2023). "In particular, SKI and PRKCZ in 1p36.33 have been reported to contribute to the loss function of TGFBR2 and SMAD4 in cancer." (PMID 26374103, 2015). "By suppressing the TGFβ signaling pathway, SKI protein could play an essential role in preventing a cancer cell from differentiating to a defined cell type." (PMID 19703312, 2009). "Some studies have accounted for predicted and validated gene targets like GATA2, SKI, NTRK3, PAK2, AR, SP1, and CDK4 that describe their involvement in cancer progression." (PMID 38741808, 2024). "Previous oncological studies suggest that SKI interacts with several core Hippo pathway components, including LATS2; however, they utilized cancer cell lines (i.e., breast, kidney, and lung)." (PMID 33847835, 2021). "Interestingly, in addition to SKI, many other putative HDAC3 deacetylation substrates have cancer related functions." (PMID 35994477, 2022).
infection (1 paper, 2025). The state of being infected such as from the introduction of a foreign agent such as serum, vaccine, antigenic substance or organism. "By targeting the SKI complex, UMB18 triggers an increase in endogenous cellular cholesterol, which disrupts the fine balance that viruses rely on for efficient infection." (PMID 40928250, 2025).
SKI also shares sentences with these, for which no sentence is quoted: intellectual deficiency (2 papers); lung carcinoma (2); age-related macular degeneration (1); aneurysm (1); Anophthalmia (1); Autoimmunity (1); Camptodactyly (1); cervical cancer (1); cholangiocarcinoma (1); chronic neutrophilic leukemia (1); connective tissue disorder (1); endometrial cancer (1); erythroleukemia (1); Esophageal Carcinoma (1); glioblastoma (1); glioma (1); left ventricular noncompaction (1); leukodystrophy (1); lung adenocarcinoma (1); multiple sclerosis (1); non-small cell lung carcinoma (1); Obesity (1); peripheral neuropathy (1); prostate carcinoma (1); T-prolymphocytic leukemia (1).